ENSG00000282998 (novel transcript)
Gene: Long non-coding RNA gene on chromosome 2 (49,202,101 to 49,562,658, reverse strand). Ensembl gene ENSG00000282998.
Gene Ontology:
Biological process: SRP-dependent cotranslational protein targeting to membrane, signal sequence recognition
Cellular component: signal recognition particle, endoplasmic reticulum targeting